FOXC1 (forkhead box C1)
Diseases named in the same sentence as FOXC1 in open-access papers (continued):
Sharing a sentence is not in itself a finding about the gene and the disease.
bladder cancer (6 papers, 2019 to 2025). "FOXC1 can induce phenotypic plasticity by binding to enhancer elements and accelerating the transition of bladder cancer cells to the cisplatin-resistant phenotype via a mutation-independent manner." (PMID 39596660, 2024). "Collectively, these findings suggest that FOXC1 regulates phenotypic plasticity by promoting a mutation-independent shift towards cisplatin resistance in bladder cancer." (PMID 35406487, 2022). "Collectively, these findings suggest that FOXC1 contributes to phenotypic plasticity by binding enhancers and promoting a mutation-independent shift towards cisplatin resistance in bladder cancer." (PMID 35406487, 2022). "In this study, we determined the expression of miR-4792 and FOXC1 and explored how their loss or overexpression would affect bladder cancer development by using multiple bladder cancer cell lines and bladder cancer tumor models." (PMID 35096062, 2022). "ABCB1, a well-known ATP-binding cassette transporter associated with cisplatin resistance in bladder cancer, is the gene with the highest differential expression after FOXC1 knockout." (PMID 35406487, 2022). "This suggests that FOXC1 binds to accessible enhancers to promote cisplatin resistance in bladder cancer cells." (PMID 39456780, 2024). "To further investigate the role of FOXC1 across bladder cancer cell lines, we analyzed FOXC1 motif enrichment at enhancers gaining accessibility in T24 SP and NSP cells." (PMID 35406487, 2022). "In summary, FOXC1 potentiates transition to the drug-resistant phenotype across multiple bladder cancer cell lines." (PMID 35406487, 2022). "Accordingly, cisplatin treatment of bladder cancer cells led to an increased FOXC1 expression, which mediated cell survival and conversion to a drug-resistant phenotype." (PMID 35406487, 2022). "In support of a functional importance of FOXC1 in bladder cancer, we found that treatment with cisplatin increased FOXC1 expression and that FOXC1 promoted conversion to the SP phenotype and cisplatin resistance in bladder cancer." (PMID 35406487, 2022). "We showed that FOXC1 is highly expressed in multiple bladder cancer cell lines and bladder tumor tissues." (PMID 35096062, 2022). "miR-4792 exposure to bladder cancer cells reduces the expression levels of FOXC1 and c-Myc, slows down cell growth, and decreases aerobic glycolysis and lactic acid content." (PMID 35096062, 2022). "To further test the importance of FOXC1 in regulating bladder cancer cisplatin resistance, we performed a series of in vitro assays that investigated the function of FOXC1 in bladder cancer cells." (PMID 35406487, 2022). "The knockdown of FOXC1 expression in bladder cancer cell lines decreases c-Myc expression levels, retards cell growth, and reduces aerobic glycolysis (also known as the Warburg effect) and lactic acid content." (PMID 35096062, 2022). "In this study, we first checked the expression level of FOXC1 in TCGA bladder cancer (BLCA) and found that the FOXC1 expression in bladder cancer was diverse." (PMID 35096062, 2022). "Here, we studied the role of miR-4792/FOXC1 signaling in bladder cancer by using multiple bladder cancer cell lines and bladder cancer mouse models through in vitro and in vivo approaches." (PMID 35096062, 2022). "FOXC1-downregulated bladder cancer cells form significantly smaller tumors in vivo." (PMID 35096062, 2022). "Therefore, FOXC1 targeting may be a new therapeutic avenue to mitigate cisplatin resistance and improve treatment efficacy in bladder cancer." (PMID 35406487, 2022). "Indeed, the significant overlap between FOXC1 binding sites and increased chromatin accessibility in SP cells suggests that FOXC1 may act as a pioneer transcription factor in bladder cancer cells that transition to cisplatin resistance." (PMID 35406487, 2022). "However, the function of miR-4792/FOXC1 signaling in bladder cancer development remains unknown." (PMID 35096062, 2022).
bladder cancer (continued). "However, the role of the miR-4792/FOXC1 axis in bladder cancer development is unknown." (PMID 35096062, 2022). "Additional bladder cancer cell lines, including T24, UMUC-3, and TCCSUP, were tested to confirm the importance of FOXC1 in regulating cisplatin resistance." (PMID 35406487, 2022). "Therefore, FOXC1 might be downstream of miR-4792 in bladder cancer." (PMID 35096062, 2022). "However, the expression status of FOXC1 in bladder cancer is unknown." (PMID 35096062, 2022). "Consistent with this possible linkage between FOXC1, the AKT pathway, and cisplatin resistance of SP cells, we have previously shown that an AKT inhibitor can reduce the transition to the SP phenotype and decrease cisplatin resistance in bladder cancer." (PMID 35406487, 2022).
hearing loss (6 papers, 2021 to 2025). "OFCD is highly variable and shows substantial overlap with combined features of the two types of ARS including missing teeth (PITX2) and hearing loss and congenital heart defects (FOXC1); while noted to be rare, umbilical hernia has occasionally been reported as well." (PMID 37895297, 2023). "The extra-ocular features seen in FOXC1-related ARS include many that are also present in 6p25 deletion syndrome, namely tooth abnormalities, sensorineural hearing loss, congenital heart defects, cerebellar abnormalities and craniofacial dysmorphisms such as maxillary hypoplasia and hypertelorism." (PMID 36964621, 2023). "Hearing loss is one of the most common non-ocular features of FOXC1-related ARS, whereas it is not commonly observed in ARS of other genetic origins." (PMID 36964621, 2023). "Furthermore, Although the affected individual present hearing loss, however, the hearing loss is conductive and is reversible during the follow-up, which might not linke to the FOXC1 variant and is coincidental." (PMID 34809627, 2021).
leukemia (6 papers, 2018 to 2025). A malignant (clonal) hematologic disorder, involving hematopoietic stem cells and characterized by the presence of primitive or atypical myeloid or lymphoid cells in the bone marrow and the blood. "The mutation of FOXC1 in T cell promoted the proliferation of leukemia cells in vitro and in vivo." (PMID 35504885, 2022). "In vivo analyses, FOXC1 significantly accelerated the onset of symptomatic leukemia by collaborating with HOXA9." (PMID 29552326, 2018). "Murine Hoxa9/FOXC1 leukemias also exhibited shortened latency versus Hoxa9/MTV leukemias, in contrast to the latencies observed for Hoxa9/IRX3 leukemias." (PMID 29346763, 2018). "Upregulated FOXC1 H446HG decreased apoptosis in leukemia cells." (PMID 35504885, 2022). "However, during leukemia, the abnormally high expression of FOXC1 in AML and the interaction between HOXA5/HOXA9, members of the Hox family, can lead to abnormal myeloid differentiation." (PMID 35504885, 2022). "Furthermore, in K562 leukemia cells which also lack FOXC1 expression, the FOXC1 promoter is occupied by the PRC2 subunits EZH2 and SUZ12." (PMID 30764547, 2019). "With regard to the morphologic classification of human AML, FOXC1-expressing leukemias were significantly less likely to exhibit monocytic lineage differentiation (i.e., FAB-M5) and significantly more likely to exhibit granulocytic lineage differentiation (i.e., FAB M2)." (PMID 29346763, 2018). "In vivo analyses, FOXC1 dramatically promoted the onset of symptomatic leukemia with HOXA9." (PMID 29552326, 2018).
nasopharyngeal carcinoma (6 papers, 2020 to 2025). A carcinoma arising from the nasopharyngeal epithelium. "A previous study showed that miR-4792 can inhibit epithelial-mesenchymal transition and invasion in nasopharyngeal carcinoma by targeting FOXC1." (PMID 35096062, 2022). "Furthermore, miR-4792 has been described to directly target the transcription factor FOXC1 in both, nasopharyngeal carcinoma cells and A549 cells." (PMID 33121145, 2020). "However, this is inconsistent with a previous report, where the expression of miR-639 was shown to be associated with the TGF-beta-induced EMT pathway, which activated metastasis in tongue squamous cell carcinoma by targeting FOXC1; this was also demonstrated in nasopharyngeal carcinoma." (PMID 34034740, 2021).
ovarian carcinoma (6 papers, 2019 to 2023). A malignant neoplasm originating from the surface ovarian epithelium. "circ-PTK2 is an important molecule in regulating the pathogenic processes of ovarian cancer via the miR-639 and FOXC1 regulatory cascade." (PMID 34034740, 2021). "Here circ-PTK2 expression was upregulated when cell migration and invasion were enhanced, indicating that miR-639 expression was downregulated, while the expression of the corresponding downstream target gene, FOXC1, was upregulated in ovarian cancer." (PMID 34034740, 2021). "Although the anti‐tumour roles of CDX1 and FOXC1 have been reported, more evidence about their function in repressing ovarian cancer should be provided in future." (PMID 33336896, 2021). "Therefore, we considered CDX1 and FOXC1 are targets of EZH2 in ovarian cancer." (PMID 33336896, 2021). "The lncRNA ATB binds to EZH2 and downregulates the expression of DAB2IP, CDH1, LATS2, FOXC1 and CDX1, thus facilitating the progression of ovarian cancer." (PMID 34890108, 2022). "However, the occurrence of ovarian cancer and the level of miR-639 and FOXC1 may be regulated by various factors and not just circ-PTK2." (PMID 34034740, 2021).
asthma (5 papers, 2019 to 2025). "Forkhead box C1 (FOXC1), a transcription factor, can promote the proliferation of airway smooth muscle cells by activating NF-kB in a mouse model of asthma." (PMID 40005151, 2025). "The study reveals that the potential molecular pathways for asthma include FOXC1-miR-PI3K/AKT, which indicates that RNF126 and PI3K/AKT pathways may have therapeutic effect in asthma." (PMID 36393974, 2022).
esophageal cancer (5 papers, 2017 to 2024). A primary or metastatic malignant neoplasm involving the esophagus. "FOXC1 knockdown augments tumor cells’ susceptibility to cisplatin, implying FOXC1’s potential utility as a bioindicator and resistance target in esophageal cancer treatment." (PMID 38413558, 2024). "Mechanistically, FOXC1 was shown to stimulate EMT in esophageal cancer cells by binding to the Zeb2 promoter directly in a pre-B-cell leukemia homeobox 1 (PBX1)-dependent manner and thereby induce its expression." (PMID 34708244, 2022). "FOXCUT and FOXC1 levels were both up-regulated in esophageal cancer and strongly correlated with poor differentiation and metastasis." (PMID 28388588, 2017). "FOXCUT plays a functional role in the development of esophageal cancer and predicts the survival potentially and partially by modulating FOXC1." (PMID 28388588, 2017). "FOXCUT level was positively correlated with FOXC1 level in esophageal cancer, and the decreased expression of FOXC1 was also observed after being treated by FOXCUT siRNA." (PMID 28388588, 2017). "Furthermore, FOXC1 has been reported to play significant role during EMT in a variety of cancers such as esophageal cancer, nasopharyngeal cancer, basal-like breast cancer, glioma, cervical cancer, and HCC." (PMID 34708244, 2022). "In vitro experiments showed that either FOXCUT or FOXC1 silencing could greatly inhibit cell proliferation, colony formation, migration and invasion in esophageal cancer cells." (PMID 28388588, 2017). "We discovered that the knockdown of FOXC1 significantly reduced the expression of CD44, and CD133 at the protein and mRNA levels, subsequently curtailing the proportion of CD44+ cells within esophageal cancer cell lines ECA-109 and KYSE-150." (PMID 38413558, 2024). "Elevated FOXC1 expression was observed in esophageal cancer tissues, and it displayed a negative correlation with the survival rates of patients., thereby intimating FOXC1’s role as a dismal prognostic determinant in ESCC." (PMID 38413558, 2024).
heart failure (5 papers, 2016 to 2025). Inability of the heart to pump blood at an adequate rate to meet tissue metabolic requirements. "Loss of function studies comparing different models with normal or abnormal heart development have also shown that lower levels of several FOX proteins, including FOXC1, is strongly associated with the pathogenesis of heart failure." (PMID 27103944, 2016). "FOXC1 TF renders individuals more susceptible to cardiac failure." (PMID 38024867, 2023). "In a study involving cardiomyocytes from patients with heart failure, FOXC1 overexpression was shown to induce cellular senescence, as well as mitochondrial and systolic dysfunction." (PMID 41030501, 2025). "Our GRNs highlight the importance of TBX3 in ischemic cardiomyopathy and FOXC1 in heart failure, both of which were previously associated with cardiac disorders but not specifically linked with cardiomyopathies or heart failure." (PMID 38673810, 2024). "Importantly, we confirmed that FOXC1 protein levels were induced and negatively correlated with myocardial telomere length in heart failure patient hearts." (PMID 38634789, 2024). "Notably, several transcription factors highlighted by our approach, such as FOXC1 in heart failure and KLF10 and KLF15 in ischemic cardiomyopathy, are supported by existing literature, validating our approach." (PMID 38673810, 2024). "FOXC1, a key transcription factor involved in early cardiogenesis, was upregulated in sTL-CMs and its protein levels were negatively correlated with telomere lengths in heart failure patients." (PMID 38634789, 2024). "In keep with our hiPSC-CM observations, telomere signal negatively correlated with FOXC1 and FOXC2 protein expressions in human heart failure biopsies." (PMID 38634789, 2024). "Moreover, FOXC1 and FOXC2 protein levels correlated positively in heart failure biopsies." (PMID 38634789, 2024).
iris hypoplasia (5 papers, 2007 to 2025). "Variable expressivity associated with FOXC1 variants may be quite broad, with the observation of Peters anomaly, iris hypoplasia, or corectopia among family members harboring the same causal variant." (PMID 35327965, 2022). "Cloning of the 6p25 breakpoint led to the identification of mutations in the FOXC1 gene (formerly called FKHL7), and they demonstrated that mutations in the FOXC1 gene were also detected in patients with Rieger's anomaly, Axenfeld's anomaly, and iris hypoplasia." (PMID 17653043, 2007). "This is supported by clinical observations where interstitial duplication of FOXC1 alone causes an iris hypoplasia phenotype, whereas duplications containing both genes (plus several others depending on the extent of the duplication) cause microcornea and ptosis, without iris hypoplasia." (PMID 22022403, 2011).
myocardial ischemia (5 papers, 2021 to 2025). A disorder of cardiac function caused by insufficient blood flow to the muscle tissue of the heart. "For example, ELAVL1 was activated by FOXC1 to promote cardiomyocyte ferroptosis during myocardial ischemia‐reperfusion injury." (PMID 40401147, 2025). "Dysregulation of FOXC1 has been reported in diseases including congenital heart defects, cancers, and myocardial ischemia." (PMID 33568052, 2021). "Moreover, several studies have reported that FOXC1 expression can be induced under conditions of myocardial ischemia." (PMID 41030501, 2025). "We next explored whether stimulation of FoxC1/Oct4 axis after cardiac ischemia enhances MEndoT of MSCs." (PMID 34454602, 2021). "Targeting ferroptosis or FOXC1/ ELAVL1 could be beneficial for myocardial ischemia patients." (PMID 33568052, 2021). "In addition, some literature suggests that FOXC1 could be induced during myocardial ischemia." (PMID 33568052, 2021).
oral squamous cell carcinoma (5 papers, 2014 to 2025). "miR-204-5p/FOXC1 has been identified as another molecular axis through which MCM3AP-AS1 contributes in the pathoetiology of oral squamous cell carcinoma." (PMID 35790972, 2022).
primary congenital glaucoma (5 papers, 2010 to 2025). "MYOC and FOXC1 mutations are not involved in pathogenesis of primary congenital glaucoma in our patients." (PMID 21031026, 2010). "This is the first study from north India showing non-involvement of MYOC and FOXC1 in the pathogenesis of primary congenital glaucoma." (PMID 21031026, 2010).
Alzheimer disease (4 papers, 2022 to 2024). A progressive, neurodegenerative disease characterized by loss of function and death of nerve cells in several areas of the brain leading to loss of cognitive function such as memory and language. "The TF FOXC1 is associated with neuroinflammation and neuronal apoptosis, whereas neuroinflammation is highly related to neurodegenerative complications such as Alzheimer’s disease, Dementia, and Parkinson’s disease." (PMID 37993790, 2023). "FOXC1, GATA2 and YY1 were found as regulatory TFs in several neurological conditions, such as Alzheimer's disease and various others." (PMID 39153206, 2024).
esophageal squamous cell carcinoma (4 papers, 2018 to 2024). Esophageal squamous cell carcinoma (ESCC) is a type of esophageal carcinoma (EC) that can affect any part of the esophagus, but is usually located in the upper or middle third. "We further analyzed FOXC1 expression in esophageal squamous cell carcinoma, esophageal adenocarcinoma, and normal esophageal tissues based on the TCGA database." (PMID 38413558, 2024). "In comparison to normal esophageal tissues, the results indicated a significant increase in FOXC1 expression in esophageal squamous cell carcinoma." (PMID 38413558, 2024). "FOXC1, in turn, promotes esophageal squamous cell carcinoma stem-like properties by transactivating CBX7 and IGF-1R." (PMID 38413558, 2024). "Furthermore, western blot analysis demonstrated elevated FOXC1 expression levels in esophageal squamous cell carcinoma cell lines (KYSE150, TE-1, ECA-109, KYSE-30) compared to the normal esophageal epithelial cell line HET-1A." (PMID 38413558, 2024). "Esophageal squamous cell carcinoma (ESCC) patients with low FOXC1 expression have a significantly better prognosis than those with high FOXC1 expression." (PMID 29552326, 2018). "This establishes a significant positive feedback loop (IGF-1/IGF-1R-FOXC1-IGF-1R), underscoring FOXC1’s potential role as a prognostic biomarker for esophageal squamous cell carcinoma." (PMID 38413558, 2024).
Intellectual disability (4 papers, 2016 to 2022). "Also, two case report studies have also shown that ring chromosome 6 encompassing FOXC1 is associated with intellectual disability, short stature, and multiple facial dysmorphisms." (PMID 35436926, 2022). "In one key study, the severity of mental retardation in patients was found to be strongly associated with the size and position of FOXC1 deletions and whether they extended further to encompass exons of the nearby GMDS gene." (PMID 27103944, 2016).
laryngeal squamous cell carcinoma (4 papers, 2018 to 2025). A squamous cell carcinoma that arises from the larynx. "An association with FOXC1, miR-204 and metastasis was also recently shown for laryngeal squamous cell carcinoma." (PMID 29382303, 2018). "Similarly, another study reported decreased miR-204-5p levels and increased FOXC1 expression in laryngeal squamous cell carcinoma (LSCC) compared to those in control cells, correlating with the cancer stage and malignancy." (PMID 40332443, 2025).
lymphoma (4 papers, 2018 to 2024). A malignant (clonal) proliferation of B- lymphocytes or T- lymphocytes which involves the lymph nodes, bone marrow and/or extranodal sites. "FOXC1 and ERK1‐2 are proteins implicated in aggressive biological behavior of various malignancies including lymphomas." (PMID 39404228, 2024). "On the other hand, research into FOXC1's role in non-Hodgkin's lymphoma centers around its interaction with Jun proteins in DLBCL, which play a role in lymphoma interaction with the microenvironment and dissemination into extra-nodal sites." (PMID 29487724, 2018).